MAGEB17 (MAGE family member B17)
Tractability: No criterion of Open Targets' tractability assessment is met for any kind of drug.
Gene: Protein-coding gene on chromosome X (16,167,481 to 16,171,464, forward strand). Ensembl gene ENSG00000182798.
Subcellular location (Human Protein Atlas): Nucleoplasm
Gene Ontology:
Biological process: negative regulation of transcription by RNA polymerase II
Cellular component: nucleus; cytoplasm
Homologues: Orthologues: chimpanzee MAGEB17 (97% identical), macaque MAGEB17 (93% identical), zebrafish ndnl2 (25% identical), Drosophila melanogaster MAGE (18% identical). Paralogues in human: MAGEB4 (55% identical), MAGEB1 (54% identical), MAGEB18 (51% identical), MAGEB2 (49% identical), MAGEB3 (49% identical), MAGEB10 (48% identical), MAGEB6B (46% identical), MAGEB6 (45% identical), MAGEB16 (45% identical), MAGEA10 (44% identical), MAGEC2 (41% identical), MAGEA11 (40% identical), and 25 more.
Diseases named in the same sentence as MAGEB17 in open-access papers:
MAGEB17 is named in the same sentence as 1 disease in open-access papers, as found by Europe PMC text mining. Sharing a sentence is not in itself a finding about the gene and the disease. The quoted sentences say what the papers report.
tumor (2 papers, 2021 to 2022). "The genes TIMP1, MAGEB17, CA3, and KRT75 expressions are relatively lower with sequence read at <100 in both cultured cells and tumor samples." (PMID 33808801, 2021). "Our analysis identified high expression of MAGEB2, MAGEC3, and MAGEB17 only in the non-viral-infected tumor group, in which we observed the overexpression of genes involved in stress response." (PMID 36557005, 2022).